KANTR (KANTR integral membrane protein)
Synonyms: Spasm; LINC01155
Gene: Protein-coding gene on chromosome X (53,094,142 to 53,170,914, forward strand). Ensembl gene ENSG00000232593.
Subcellular location: Membrane
Gene Ontology:
Cellular component: membrane
Homologues: Orthologues: rabbit KANTR (100% identical), pig KANTR (99% identical), mouse Kantr (96% identical), rat Kantr (96% identical).
Diseases named in the same sentence as KANTR in open-access papers:
KANTR is named in the same sentence as 1 disease in open-access papers, as found by Europe PMC text mining. Sharing a sentence is not in itself a finding about the gene and the disease. The quoted sentences say what the papers report.
infection (1 paper, 2023). The state of being infected such as from the introduction of a foreign agent such as serum, vaccine, antigenic substance or organism. "Metabolite compositional changes occurred between KATR and KANTR samples as shown by the feature exclusiveness in Venn diagram which reflected 8487 (47.7%) infection-exclusive, 8742 (49.1%) non-infection exclusive and only 583 (3.3%) common metabolite features indicating metabolite variability." (PMID 38030710, 2023).